PTH (parathyroid hormone)
Diseases named in the same sentence as PTH in open-access papers (continued):
Sharing a sentence is not in itself a finding about the gene and the disease.
parathyroid tumors (continued). "Parathyroid tumors are heterogeneous in the severity of PTH secretion, cell proliferation, and genetic background." (PMID 37065733, 2023). "She underwent an uncomplicated second trimester parathyroid tumour excision with normalization of post op PTH." (PMID 36284286, 2022). "They normally regress after normalization of serum calcium and PTH, following surgical removal of parathyroid tumor(s)." (PMID 32326947, 2020). "Removing the parathyroid tumor significantly lowers the levels of parathyroid hormone (PTH) in blood, and thereby decreases serum calcium." (PMID 33112830, 2020). "Patients with sporadic parathyroid tumors had larger tumor sizes and higher levels of PTH and calcium than patients with hereditary parathyroid tumors." (PMID 30104706, 2018). "Given that miR-199b-5p was differentially expressed according to the parathyroid tumor type, we further analyzed the correlation between miR-199b-5p and PTH levels." (PMID 30104706, 2018). "The laboratory results showed higher PTH and calcium levels in patients with parathyroid tumors than in normal controls." (PMID 30104706, 2018). "Parathyroid tumours in Cdc73+/−, Cdc73+/L/PTH-Cre and Cdc73L/L/PTH-Cre mice had significantly increased proliferation, with rates >fourfold higher than that in parathyroid glands of wild-type littermates (P<0.0001)." (PMID 28288139, 2017). "Parathyroid tumour development, and elevations in serum calcium and PTH, were similar in males and females." (PMID 28288139, 2017). "Previously, studies have found both lower and higher PTH mRNA expressionin parathyroid tumors as compared with normal parathyroids." (PMID 26865585, 2016). "We aimed to investigate the potential relationship between parathyroid tumor PTH secretion,PTH gene expression, and patient clinical parameters in a large, well-characterized cohort ofparathyroid tumors." (PMID 26865585, 2016). "To examine the relationship between PTH production and calcium responsiveness in individual parathyroid tumor cells, we probed functionally interrogated tissue sections for PTH abundance." (PMID 27537691, 2016). "The main regulator of PTH secretion is calcium andthe calcium–PTH set point is shifted in parathyroid tumor cells." (PMID 26865585, 2016). "A total of 154 parathyroid tumors were analyzed by PTH immunohistochemistry and chromogenicin situ hybridization of PTH mRNA." (PMID 26865585, 2016). "The symptoms and signs of hematoma from a parathyroid tumor depend on the anatomical position of the tumor, the amount of bleeding and the increase or decrease in secretion of PTH accompanying the infarction and/or bleeding in the gland." (PMID 26610856, 2015). "A possible effect on PTH secretion from prolactin stimulation of short-term cultured parathyroid tumour cells was studied by parallel perifusion at two different prolactin concentrations (100 or 200 μg/L)." (PMID 22606260, 2012). "The VDR baT haplotype has been related to enhanced abnormality in the calcium regulation of the parathyroid hormone secretion from adenomatous parathyroid cells of primary human parathyroid tumor." (PMID 16507122, 2006). "This study aimed to determine whether the extent of intraoperative parathyroid hormone (PTH) decline, measured 15 min after parathyroid tumor excision, could serve as a reliable intraoperative rule-out marker for PEH." (PMID 41750783, 2026). "Parathyroid tumor volume was thus seen to increase as intact PTH increases." (PMID 38525667, 2025). "Before the operation, the levels of serum calcium, parathyroid hormone, growth hormone, and other hormones should be actively measured to screen for the presence of pituitary tumors and parathyroid tumors to exclude the possibility of multiple endocrine neoplasia." (PMID 39749032, 2024). "Nevertheless, preoperative calcium and PTH measurements allowed to suspect a parathyroid tumor." (PMID 37183888, 2023).
parathyroid tumors (continued). "Wallace also hypothesize lower PTH setpoints in some patients and anatomic barriers in local circulation around a parathyroid neoplasm." (PMID 31074404, 2019). "Lymphocyte infiltrates significantly correlated to higher levels of patient’s levels of PTH and could potentially indicate a cytokine mediated change in parathyroid tumor cell endocrine activity." (PMID 28855268, 2017). "Moreover, 75% of the parathyroid tumours were APAs, and thus these Cdc73+/− mice with the conditional Cdc73+/L/PTH-Cre and Cdc73L/L/PTH-Cre mice provide important in vivo models for this rare but difficult to treat human neoplasm." (PMID 28288139, 2017). "All parathyroid tumors and normal rims expressed PTH protein and PTH mRNA." (PMID 26865585, 2016). "Because uncoupling of calcium sensing from PTH production is the causative physiological defect in PHPT, we next determined whether PTH abundance was suppressible in live parathyroid tumor tissue in response to elevated calcium." (PMID 27537691, 2016). "Although some reports have stated that preoperative intact PTH value may be useful in predicting parathyroid tumor volume, the interpretation of research findings among researchers has been quite inconsistent, particularly between those few large studies with ≥500 cases." (PMID 38525667, 2025). "Hence, the complex interplay between magnesium status and PTH profile, including in pathological conditions such as parathyroid tumour, might be an important, yet incompletely understood, contributor to the overall clinical picture." (PMID 39051301, 2024). "Primary hyperparathyroidism (PHPT), due to a persistent PTH hypersecretion independent from serum calcium levels, is a pathological idiopathic condition indicative of the presence of hyperactive/hypercellular gland(s) (parathyroid hyperplasia) or parathyroid tumors." (PMID 34681865, 2021). "The results from the limited sample set examined here could indicate that the extent of calcium-PTH signaling axis failure in parathyroid tumors may vary among PHPT patients, although larger studies will clearly be required before any clinical conclusions can be drawn." (PMID 27537691, 2016). "At least 7 investigations have reported on the correlations between preoperative serum intact PTH or calcium values in patients with PHPT and the volume or weight of the responsible parathyroid tumor." (PMID 38525667, 2025). "While these relationships have been previouslypresented, this study is the first to integrate both PTH IHC and CISH with patients’clinical chemistry in a well-characterized large cohort of parathyroid tumors." (PMID 26865585, 2016). "Thus, the incremental prognostic contribution of the 15-min PTH decline beyond ALP and parathyroid tumor weight appears limited." (PMID 41750783, 2026). "That said, when we added ALP and parathyroid tumor weight to the multivariate models, PTH decline no longer predicted independently." (PMID 41750783, 2026). "When there are elevated levels of PTH, the next step would be to conduct thyroid imaging and Sestamibi scans to rule out parathyroid tumours." (PMID 40142228, 2025). "With regard to ioPTH monitoring, particularly for mediastinal parathyroid tumors, there is no consensus on the degree and timing of PTH reduction that indicates successful surgery." (PMID 40062044, 2025). "The change on plasma glucose, fasting insulin, HOMA-IR, HOMA-B%, and adiponectin did not correlate with the change in calcium or PTH as corrected upon parathyroid tumour removal." (PMID 40283231, 2025). "Suspicious findings include markedly elevated calcium and parathyroid hormone (PTH) levels, end-organ damage, or unusually large parathyroid tumors, with more than three-quarters of patients having a palpable neck mass on physical examination (on average above 3 cm in size)." (PMID 40530390, 2025). "Regarding PTH, it is detectable immunohistochemically and almost always present in parathyroid tumours and tissues while being absent from thyroid gland." (PMID 35805976, 2022).
parathyroid tumors (continued). "Parathyroid adenoma was diagnosed if a single encapsulated or demarcated, non-invasive parathyroid neoplasm lacking intralesional adipose tissue was found in a patient experiencing surgery-related decrease of the parathyroid hormone level." (PMID 35805976, 2022). "Herein, we describe the nature and function of a novel lncRNA detected downstream of the human parathyroid hormone (PTH) gene in both extremely rare ectopic PTH-producing retroperitoneal malignant fibrous histiocytoma and parathyroid tumors with PTH overproduction." (PMID 35618021, 2022). "No areas with apparently higher PTH expression were identified, perhaps suggesting thathyper functioning parathyroid tumor subclones should be rare." (PMID 26865585, 2016). "Consistent with a previous report on the correlation between PTH and tumor volume, PTH levels were correlated significantly with tumor size in patients with sporadic parathyroid tumors (γ = 0.592, P = 0.002) but not significantly in patients with hereditary parathyroid tumors." (PMID 30104706, 2018). "However, this paradigm fails to explain intrinsic tonic PTH secretion at low [Ca2+]e under normal physiological conditions, when homomeric CaSRs are inactive or why, in many cases of PHPT, the causative parathyroid tumors retain normal Ca2+-responsiveness despite their elevated tonic PTH production." (PMID 40492090, 2025).
magnesium deficiency (59 papers, 2010 to 2026). A nutritional condition produced by a deficiency of magnesium in the diet, characterized by anorexia, nausea, vomiting, lethargy, and weakness. "Magnesium deficiency frequently coexists with phosphate depletion and has been associated with impaired parathyroid hormone activity, intracellular shifts, and reduced renal phosphate reabsorption." (PMID 41416290, 2025). "The lowered PTH secretion caused by magnesium deficiency contributes to a decrease in bone formation." (PMID 39051301, 2024). "Its levels begin to rise very early in CKD, before the alterations in calcium, phosphorus, and PTH levels, and, in addition, its production is stimulated by reduced oxygenation, iron deficiency, and Epo." (PMID 39684548, 2024). "PTH plays a central role in calcium homeostasis, and impaired PTH function due to magnesium deficiency can result in reduced calcium absorption from the intestine and increased calcium loss through the kidneys." (PMID 37760804, 2023). "It stimulates osteoblasts and influences the secretion of parathyroid hormone (PTH) and vitamin D. Magnesium deficiency increases the activity of osteoclasts, which contributes to bone loss." (PMID 36556694, 2022). "In vivo, other positive regulators of FGF-23 include inflammatory related cytokines such as IL-1β, TNF-α, lipopolysaccharides (LPS), mineral mediators like parathyroid hormone (PTH), 1,25(OH)2D and hematopoietic factors such as hypoxia or iron deficiency." (PMID 36246903, 2022). "Five nodes were identified as relevant to kidney function via analysis of the hub neighborhoods: iron deficiency, PTH, urea, uric acid, and C-reactive protein." (PMID 36230609, 2022). "Nutritional status, inflammation, iron deficiency, uremia, high parathyroid hormone (PTH) levels, and comorbidities such as malignancy have been shown to contribute." (PMID 36532527, 2022). "Magnesium deficiency is a well-documented cause of a blunted PTH response as it inhibits PTH synthesis and secretion." (PMID 34580590, 2021). "Magnesium deficiency has also been considered to be a potential cause of low PTH levels as magnesium participates in PTH secretion and action through interaction with the calcium sensing receptor." (PMID 32219087, 2020). "There are several possible explanations for the reduced PTH levels that we observed in 35% of our patients with AN including: high calcium intake, magnesium deficiency, higher vitamin D levels and net loss of calcium from bone." (PMID 32219087, 2020). "Overall, 29/180 patients (16.11%) had magnesium deficiency and 24/193 (12.43%) calcium deficiency, 18.28% of patients (32/175) had PTH levels above the upper normal range and 70/115 (60.86%) had CRP levels above the upper normal range." (PMID 30323223, 2018). "In support of this suggestion are observations that magnesium deficiency is associated with insufficient PTH action and can lead to reduced responses to calcitropic hormones." (PMID 28402956, 2017). "Magnesium is also a major participant in the calcium-PTH axis, and in critical patients, nutritional deficiency and organ dysfunction can lead to magnesium deficiency." (PMID 24073266, 2013). "Magnesium deficiency can also decrease the activity of magnesium-dependent enzymes, inhibiting PTH synthesis and regulation." (PMID 24073266, 2013). "Magnesium deficiency reduces the PTH effect in the kidneys and bones and increases its degradation in the liver and kidneys." (PMID 21181066, 2010). "In addition, magnesium deficiency affects the absorption of vitamin D and PTH, which affects the absorption of calcium and bone density." (PMID 39507513, 2024). "Furthermore, magnesium deficiency can interfere with parathyroid hormone (PTH) secretion and action." (PMID 37760804, 2023). "Magnesium deficiency leads to a reduction in 1.25(OH)2D and impairs the response of PTH." (PMID 37446123, 2023). "Magnesium deficiency leads to a reduction in 1.25(OH)2D levels and an impaired PTH response." (PMID 37446123, 2023).
magnesium deficiency (continued). "In hemodialysis patients, ferric citrate significantly reduced iFGF23 levels compared to lanthanum carbonate, although serum phosphate, calcium, and PTH levels were unchanged in both groups, suggesting that the decrease in iFGF23 levels were caused by improvement in iron deficiency." (PMID 36831276, 2023). "Magnesium deficiency makes it difficult to form a parathyroid hormone that mobilizes calcium." (PMID 36288147, 2022). "Magnesium deficiency is associated with impaired secretion and affinity of PTH." (PMID 28545530, 2017). "The authors speculate that the skeletal effects of magnesium deficiency, in part, result from impaired PTH secretion, and direct and indirect effects (via PTH) on 1,25(OH)2D production resulting in impaired osteoblast production and reduced calcium absorption." (PMID 26253749, 2015). "Magnesium deficiency is related to decreased PTH and vitamin D levels." (PMID 25157571, 2014). "It has been proposed that magnesium deficiency is associated with impaired PTH secretion." (PMID 24304609, 2013). "Magnesium deficiency may also upregulate PTH, which is associated with muscle loss." (PMID 35889841, 2022). "Notably, several stimuli couple increased FGF23 transcription with increased post-translational cleavage, including inflammation, iron deficiency, erythropoietin, and parathyroid hormone, resulting in elevated concentrations of circulating total FGF23 but not intact FGF23." (PMID 31487315, 2019). "In contrast, the expression levels of parathyroid hormone (PTH) and tartrate-resistant acid phosphatase 5B (TRAP) were upregulated in iron-deficient rats, suggesting that severe iron deficiency leads to increased bone resorption as bone formation decreases." (PMID 35941905, 2022). "Low magnesium may reduce the activity of parathyroid hormone or cause resistance to parathyroid hormone (PTH), and long-term magnesium deficiency inhibits the release of PTH." (PMID 31320908, 2019). "Iron deficiency and elevated levels of EPO were major determinants of FGF23 levels, to a greater extent than more established determinants such as renal function and serum calcium, PTH, and phosphate." (PMID 31170159, 2019). "Additionally, magnesium deficiency can directly impact bone function, reducing calcium release regardless of PTH levels." (PMID 40388464, 2025). "Magnesium deficiency among those with a blunted PTH response cannot be ruled out as the magnesium loading test, which may have better reflected body stores, was not performed." (PMID 34580590, 2021).
renal osteodystrophy (54 papers, 2005 to 2026). Abnormalities of bone mineral metabolism associated with chronic kidney disease. "Adynamic bone disease, a variant of renal osteodystrophy, is the result of persistent inhibition of PTH release, which in turn is determined by constantly increased serum calcium levels." (PMID 38785509, 2024). "High PTH not only easily leads to renal osteodystrophy, but also can cause extensive calcification and LVH in cardiovascular system, which is an important factor aggravating the death of dialysis patients." (PMID 35033017, 2022). "Therefore, a new mass spectrometry-based assay, which is capable of specifically measuring the whole spectra of PTH fragments, can potentially improve diagnostic accuracy for renal osteodystrophy." (PMID 31637056, 2019). "The abnormally high level of PTH early in the course of CKD projects two progressive outcomes: renal osteodystrophy and cardiovascular disease." (PMID 38785509, 2024). "CKD-MBD is characterized by aberrant calcium, phosphate, parathyroid hormone (PTH), and vitamin D metabolism, dysfunctional bone turnover with disturbances in osteoclast/osteoblast balance (renal osteodystrophy), and vascular calcification." (PMID 39433982, 2024). "This association supports the established pathophysiology where elevated PTH, while critical for maintaining calcium homeostasis, negatively impacts bone health, potentially resulting in renal osteodystrophy." (PMID 39484207, 2024). "PTH is a central component of the pathogenesis of renal osteodystrophy and it is the major factor driving the high turnover remodeling state seen in late CKD and CKD treated with hemodialysis." (PMID 36776982, 2023). "Due to deleterious effects of very high PTH levels on bone (renal osteodystrophy), selected patients with SHPT need parathyroid gland removal as an ultimate attempt to arrest this severe complication." (PMID 31311533, 2019). "Nevertheless, a sizeable proportion of CKD patients still experience renal osteodystrophy despite having serum PTH levels within the recommended range." (PMID 31637056, 2019). "Univariate analysis showed that pruritus, lumbar X-ray changes of renal osteodystrophy, pre- and post-operative intact parathyroid hormone (iPTH), Calcium, alkaline phosphatase, and gland mass were significantly different between SH and non-SH groups." (PMID 29773914, 2018). "At the early stage, improvement of renal osteodystrophy would be an expected consequence of effectively suppressing PTH with phosphate binders, calcitriol analogs and calcimimetics." (PMID 29907149, 2018). "The implications of the elevation of PTH are the emergence of bone complications such as renal osteodystrophy, vascular calcifications, cardiovascular disease and an increase in mortality 21,22." (PMID 27821896, 2016). "As a disturbed phosphate metabolism and abnormal parathyroid hormone (PTH) levels, either low or high, contribute to vascular calcification and renal osteodystrophy, the effect of different phosphate binding agents need to be evaluated on both pathologies." (PMID 25229549, 2014). "Metabolic acidosis, which is known to correlate with renal osteodystrophy, has been shown to favor PTH actions such as increasing osteoclastic activity and reducing vitamin D levels." (PMID 15947836, 2005). "Elevated PTH levels are caused by low calcium and high phosphorus levels induced by GFR in patients with ESRD, which increases the secretion of secondary PTH, which is the underlying etiology of renal osteodystrophy." (PMID 38482569, 2024). "In addition, experimental studies have demonstrated that long-term lanthanum carbonate treatment inhibited serum PTH and led to renal osteodystrophy." (PMID 36827665, 2023). "Its subsequent connection to albuminuric patients reported in 1883 later became renal osteodystrophy in 1942, launching studies that elucidated the functions of vitamin D and parathyroid hormone and their role in the altered calcium and phosphate metabolism of the disease." (PMID 36466709, 2022).